MTOR (mechanistic target of rapamycin kinase)
Diseases named in the same sentence as MTOR in open-access papers (continued):
Sharing a sentence is not in itself a finding about the gene and the disease.
osteosarcoma (continued). "The synergistic anti-osteosarcoma activity of Rg3 and doxorubicin was also investigated in vitro and in vivo model of osteosarcoma by regulating mTOR/HIF-1α/VEGF and EMT signaling pathways." (PMID 40507179, 2025). "The PI3K/Akt/mTOR signaling pathway plays a critical role in the pathogenesis and progression of osteosarcoma." (PMID 40283955, 2025). "Other studies have explored the effects of natural compounds, such as honokiol and alantolactone, which induce apoptosis and autophagy in osteosarcoma cells through the inhibition of the PI3K/Akt/mTOR pathway." (PMID 40283955, 2025). "For example, the dual PI3K/mTOR inhibitor NVP-BEZ235 was found to inhibit osteosarcoma cell proliferation and improve survival rates in vivo." (PMID 40283955, 2025). "As an E3 ubiquitin ligase, TRIM17 promotes FTO ubiquitination and degradation, thereby activating the AKT/mTOR pathway to drive osteosarcoma progression." (PMID 41145484, 2025). "Previous studies demonstrated S100A10-ANXA2 interaction activates AKT/mTOR signaling and enhances glycolytic metabolism in osteosarcoma cells." (PMID 41195005, 2025). "In conclusion, TRIM17 promotes FTO degradation via ubiquitination, a post-translational modification, and positively modulates the AKT/mTOR signaling pathway, thereby enhancing osteosarcoma malignancy." (PMID 41145484, 2025). "Among the spectrum of molecular changes that occur in the pathological landscape of osteosarcoma, the oncogenic activation of mTOR signaling significantly contributes to osteosarcoma progression and metastasis." (PMID 40002808, 2025). "In particular, recent canine-specific transcriptomic studies have confirmed activation of PI3K and mTOR pathways in osteosarcoma, reinforcing the biological relevance of this regulatory axis in the canine setting." (PMID 40862758, 2025). "While the expression patterns, functional significance, and underlying mechanisms of MNAT1 remain entirely unexplored in OSCC, it has been demonstrated to promote proliferation and cisplatin resistance in osteosarcoma by modulating the PI3K/Akt/mTOR pathway." (PMID 41235252, 2025). "Everolimus, a pivotal mTOR inhibitor, integrates antitumor, osteoprotective, and immunomodulatory actions in osteosarcoma, targeting oncogenic signaling, metabolic reprogramming, angiogenesis, and the bone–immune interface." (PMID 40979744, 2025). "Additional predicted targets of miR-30a and miR-30e within this pathway include PIK3CA, mTOR, FOXO3, MMP13, SOX9, BCL2, VEGFA, and CCND1, all of which have been previously associated with osteosarcoma pathogenesis." (PMID 40862758, 2025). "For mechanisms, Prkci positively activates the Akt/mTOR signaling pathway in osteosarcoma; Prkci regulates the activity of the oncogenic transcription factor YAP1 by modulating binding of YAP1 to AMOT130 in ovarian cancer." (PMID 41188443, 2025). "FABP5 promotes growth in osteosarcoma through the Akt/mTOR pathway and mediates therapy resistance in medulloblastoma, underscoring its role in tumor survival and progression." (PMID 40370434, 2025). "Conversely, in osteosarcoma(OS), LXRα functions as a tumor suppressor, with its activation reducing proliferation and sensitizing tumors to chemotherapy through mTOR signaling modulation." (PMID 40370434, 2025). "It is worth emphasizing that the conclusion in this study that TRIM17 promotes the progression of osteosarcoma by activating the mTOR pathway is highly consistent with previous studies." (PMID 41145484, 2025). "The PI3K/Akt/mTOR signaling pathway is often dysregulated in osteosarcoma, facilitating cellular proliferation, survival, and resistance to therapeutic agents." (PMID 41346999, 2025).
osteosarcoma (continued). "In vitro rescue assays revealed that FTO overexpression partially reversed TRIM17-induced activation of the AKT/mTOR signaling pathway and attenuated osteosarcoma malignancy." (PMID 41145484, 2025). "Collectively, these discoveries have constructed a robust framework bridging molecular insights to therapeutic innovation, positioning the PI3K/AKT/mTOR pathway as a cornerstone for targeted therapy in malignancies, including osteosarcoma." (PMID 40979744, 2025). "In conclusion, TRIM17 likely modulates osteosarcoma malignancy through regulation of the AKT/mTOR signaling pathway." (PMID 41145484, 2025). "While, researchers also have found that AIM2 suppresses tumor cell malignant biological properties by inactivating PI3K/AKT/mTOR pathway in osteosarcoma cells." (PMID 39222064, 2024). "Knockdown of PRKCI inhibited the proliferation of osteosarcoma cells by inactivating the Akt/mTOR signaling pathway, suggesting that PRKCI was a potential target for osteosarcoma therapy." (PMID 39015499, 2024). "Ginsenoside can also inhibit the PI3K/Akt/mTOR signaling pathway, induce cell autophagy, and apoptosis, thereby suppressing the development of osteosarcoma." (PMID 38800967, 2024). "TRIM2 in osteosarcoma reduces Bcl-2-interacting mediator (Bim) expression and causes excessive proliferation of cancer cells via the PI3K/AKT/mTOR signalling pathway." (PMID 38893070, 2024). "Overall, these results suggest that PRKCI depletion inhibits osteosarcoma cell growth via inactivation of the Akt-mTOR pathway." (PMID 39015499, 2024). "Previous studies have indicated that elevated levels of OIP5-AS1 induce resistance to oxaliplatin in CRC and enhance resistance to cisplatin in osteosarcoma cells by activating the LPAATβ/PI3K/AKT/mTOR signaling axis." (PMID 39246994, 2024). "Here, we have found that the Akt-mTOR signaling pathway was involved in the inhibitory effect of PRKCI on osteosarcoma in vitro." (PMID 39015499, 2024). "For example, rapamycin and ATO can decrease the inhibitory effect of PI3K/AKT/mTOR signaling pathway on autophagy for the treatment of osteosarcoma." (PMID 38800967, 2024). "In osteosarcoma, the mTOR pathway has been extensively studied, and it has been associated with cell proliferation, inhibition of apoptosis, autophagy inactivation, and metastasis initiation." (PMID 38534381, 2024). "Expression of K17 increased the Akt/mTOR/hypoxia-inducible factor (HIF)-1α pathway in osteosarcoma cells, and knockout of K17 restored this pathway expression." (PMID 38730319, 2024). "More recently, it has been reported that DATS significantly inhibits proliferation, migration, and EMT, promotes cell apoptosis, and induces autophagy in osteosarcoma cells trough the inactivation of the EGFR/PI3K/AKT/mTOR pathway." (PMID 38786044, 2024). "MK2206 treatment significantly reduced the levels of p-AKT, p-mTOR, N-cadherin, and vimentin in osteosarcoma cells, while overexpression of HSPD1 partially abrogated these inhibitory effects." (PMID 39430254, 2024). "The findings suggest that AIM2 suppresses osteosarcoma progression through the inactivation of the PI3K/AKT/mTOR signaling pathway." (PMID 39600708, 2024). "Together, overexpressed YME1L promotes osteosarcoma cell growth, possibly by maintaining mitochondrial function and Akt-mTOR activation." (PMID 38769124, 2024). "The expression of p-mTOR in osteosarcoma tissues and adjacent normal tissues of 20 patients was detected by the IHC to further explore its role in human osteosarcoma." (PMID 39015499, 2024). "For instance, TRIM22 has been shown to inhibit osteosarcoma progression by activating the ROS/AMPK/mTOR/autophagy signaling pathway through weakening Nrf2 protein stability." (PMID 39667820, 2024). "Restoring Akt-mTOR activation by S473D constitutively active Akt1 mitigated YME1L shRNA-induced anti-osteosarcoma cell activity." (PMID 38769124, 2024).
osteosarcoma (continued). "Further, in vitro functional rescue experiments and WB assays have shown that HSPD1 promotes the proliferation and invasion of osteosarcoma cells through ATP5A1-mediated activation of mTOR signaling." (PMID 39430254, 2024). "The current targeted therapy for POB is similar to that for common osteosarcoma and focuses on the following targets: The mammalian target of rapamycin (mTOR) protein can hinder the growth of tumors by controlling the cell cycle of tumor cells." (PMID 39568569, 2024). "It suggested that PRKCI was closely related to the tumorigenicity of osteosarcoma, and the Akt/mTOR signaling pathway was involved in this process." (PMID 39015499, 2024). "Considering the composition of prognostic model, it is reported that EEF1D overexpression promotes osteosarcoma cell proliferation by facilitating Akt-mTOR and Akt-bad signaling." (PMID 38213729, 2024). "In osteosarcoma, mTOR promotes cell growth and proliferation, induces cell metastasis, inhibits apoptosis, and suppresses autophagy." (PMID 38212768, 2024). "We demonstrated that ATP5A1 knockdown resulted in reduced ATP production and impaired mTOR phosphorylation in osteosarcoma cells, whereas ATP supplementation partially restored mTOR signaling." (PMID 39430254, 2024). "Several mTOR inhibitors have been evaluated in clinical studies in osteosarcomas, including ridaforolimus, sirolimus, everolimus, and temsirolimus, either as a single-agent therapy or in combination with chemotherapy or other targeted therapies." (PMID 37109122, 2023). "DDIT4 knockout rescues the inhibitory effects of the NR modulators on mTOR phosphorylation, downstream S6 phosphorylation and osteosarcoma cell growth, indicating that the NR/DDIT4/mTOR axis plays a key role in the antitumour effects of the NR modulators." (PMID 36681687, 2023). "Most of these pathways, as well as the mTOR pathway, have been shown to play key roles in the development of osteosarcoma." (PMID 36681687, 2023). "The inhibition of the PI3K/mTOR pathway, by chemical or genetic approaches, has been demonstrated to be a sensitive and effective approach for osteosarcoma treatment." (PMID 36681687, 2023). "Their inhibitory effects were mainly achieved by specifically targeting the corresponding NRs and repressing abnormal activation of the PI3K/AKT/mTOR and ERK/mTOR pathways in osteosarcoma cells." (PMID 36681687, 2023). "Everolimus, a selective mTOR inhibitor, was used to treat unresectable high-grade osteosarcomas after standard treatment with Sorafenib." (PMID 37681936, 2023). "In this study, a total of four transcriptional osteosarcoma-related DNA sequences were screened out, which were mTOR, OGG1, EGFR, and PDGFR-β." (PMID 37065446, 2023). "Silencing of BZW2 retarded cell growth in osteosarcoma through regulating the Akt/mTOR signaling pathway." (PMID 36473368, 2023). "Functionally, RILP inhibits proliferation, migration, invasion, and promotes autophagy in osteosarcoma cells via Grb10-mediated inhibition of the PI3K/AKT/mTOR signaling pathway." (PMID 37789274, 2023). "Reduced expression of miR-144 miR-375-3p in osteosarcoma cells leads to PI3K/AKT/mTOR pathway aberrant activation, which affects OS cell proliferation, apoptosis and autophagy." (PMID 37404761, 2023). "Whole-exome, whole-genome, and RNA-sequencing of 59 pairs of tumour tissues and normal tissues revealed PI3K/AKT/mTOR as the most common pathway that is altered in osteosarcoma." (PMID 36681687, 2023). "The results showed that PDGF/PDGFR-β promoted aerobic glycolysis in osteosarcoma cells mainly through the activation of PI3K/AKT/mTOR/c-Myc pathway." (PMID 37404761, 2023).
osteosarcoma (continued). "There is evidence showing that the mTOR signaling pathway plays a significant role in a number of diseases, including osteosarcoma." (PMID 37081847, 2023). "DDIT4 has been demonstrated to regulate cell proliferation and survival by inhibiting the activity of the mTOR complex, suggesting its critical role in the inhibition of osteosarcoma by the NR modulators." (PMID 36681687, 2023). "Osteosarcoma-associated genes that were identified in a genetic analysis of 119 primary tumours and 134 metastatic nodules are also enriched in the PI3K/mTOR and MAPK pathways." (PMID 36681687, 2023). "In conclude, RILP restrains osteosarcoma progression via Grb10-mediated inhibition of the PI3K/AKT/mTOR pathway." (PMID 37789274, 2023). "TRIM22 inhibits osteosarcoma development by aggravating proteasomal degradation of NRF2 to motivate ROS/AMPK/mTOR/autophagy signaling, which results in autophagic cell death in osteosarcoma." (PMID 36870986, 2023). "We further verified that overexpression of RILP restrained the PI3K/AKT/mTOR signaling pathway and induced autophagy in osteosarcoma cells, while the opposite trend was observed when PI3K pathway activator 740Y-P was used." (PMID 37789274, 2023). "The immunoblotting results showed that all the NR modulators dramatically reduced the levels of phosphorylated mTOR in the osteosarcoma cell lines." (PMID 36681687, 2023). "Another report shows AURKB knockdown resulted in a reduction in migratory and invasive ability of osteosarcoma cell line by through mTOR/ULK1 pathway." (PMID 35332150, 2022). "For example, LHX2 is part of the mTOR signaling pathway in osteosarcoma, but has yet to be studied in placenta although the mTOR signaling pathway is known to be involved in nutrient transport in the placenta." (PMID 36622342, 2022). "Both statistical models corroborated previous studies that implicate IGF-1R/mTOR in aggressive osteosarcoma." (PMID 35284040, 2022). "In summary, 1,3,5-triazine analogs were identified as new PI3K/mTOR inhibitors against osteosarcoma." (PMID 35656180, 2022). "Our aim was to characterize the mTOR profile and certain metabolic alterations in pediatric osteosarcoma to determine the interactions between the mTOR pathway and metabolic pathways." (PMID 35392503, 2022). "Inhibition of mTORC1/2 or knockdown of mTOR or rictor prevents proliferation in osteosarcoma cell lines, and the combination of mTOR kinase inhibitor PP242 with cisplatin leads to synergistic antitumor activity." (PMID 35392503, 2022). "Our data, thus, suggest that EFEMP2 partly targets STEAP2 to promote osteosarcoma progression by inducing EMT via the PI3K/AKT/mTOR axis." (PMID 36316642, 2022). "Despite encouraging preclinical data, mTOR inhibitor monotherapies and combined therapies have shown poor antitumor effect in the treatment of osteosarcoma." (PMID 35392503, 2022). "KRT17 also activates the Akt/mTOR/hypoxia-inducible factor 1α (HIF1α) pathway by promoting proliferation and the Warburg effect, thereby promoting the growth of osteosarcoma cells." (PMID 35281081, 2022). "The PI3K/AKT/mTOR pathway is implicated in AIM2-mediated proliferation, invasion, migration, and apoptosis in osteosarcoma cells." (PMID 36568515, 2022). "Cordycepin activated the AMPK pathway and suppressed the AKT/mTOR signaling pathway, which inhibited the growth of osteosarcoma cells." (PMID 36500262, 2022). "Sulfated alginate oligosaccharide exerted autophagy induction by inactivating MEK1/ERK/mTOR signaling in osteosarcoma." (PMID 36522638, 2022). "The compounds were synthesized in a straight-forward two-step reaction and subsequently tested against PI3K and mTOR kinase and anticancer activity against osteosarcoma cells (MG-63, U2-OS, and Saos-2)." (PMID 35656180, 2022).
osteosarcoma (continued). "It negatively regulates the phosphatidylinositol 3-kinase (PI3K)/protein kinase B (AKT)/mammalian target of rapamycin (mTOR) pathway in osteosarcoma." (PMID 35879346, 2022). "The mTOR pathway is critical in tumor survival and progression, and it is potentially activated in osteosarcoma, as it has been already reported, although the mechanisms of this activation are poorly understood." (PMID 35392503, 2022). "Our aim was to characterize the mTOR and metabolic profile of osteosarcoma cases, and to determine potential targets for personalized therapies." (PMID 35392503, 2022). "Studies have found that phosphatidylinositol-3-kinase (PI3K)/Akt and the mammalian target of rapamycin (mTOR) are aberrantly activated in osteosarcoma." (PMID 35656180, 2022). "These experiments demonstrated that a reduction in either STEAP2 or Akt or both inhibited EMT and PI3K/Akt/mTOR axis activation in osteosarcoma cells even when treated with exogenous EFEMP2." (PMID 36316642, 2022). "EMT is a key factor in oncocyte migration and invasion, and downregulation of STEAP2 represses EMT through reduced PI3K/AKT/mTOR axis activity, which in turn reduces osteosarcoma cell migration and infiltration." (PMID 36316642, 2022). "In conclusion—based on our results—we suggest performing detailed mTOR profile characterization before administering mTOR inhibitor therapy for osteosarcoma patients." (PMID 35392503, 2022). "In conclusion, sulfated alginate oligosaccharide exerts antitumor activity and autophagy induction by inactivating MEK1/ERK/mTOR signaling in a KSR1-dependent manner in osteosarcoma." (PMID 35418575, 2022). "Numerous preclinical data suggest the importance of mTOR activity in osteosarcoma cell proliferation and survival." (PMID 35392503, 2022). "Functionally, ginsenoside Rh2 enhances apoptosis of U20S cells through increasing activity of MAPK pathway and suppressing activities of PI3K/AKT/mTOR and NF‐кB pathways in osteosarcoma cells." (PMID 35220526, 2022). "To further determine how AOS-SO4 regulated the MEK1/ERK/mTOR pathway in osteosarcoma, we searched related literature and the STRING website and reported that MEK1 interacted with KSR1, which is also an important autophagy regulator." (PMID 35418575, 2022). "The results showed that KRT17 knockout inhibited the proliferation and glycolysis of osteosarcoma cells by inhibiting the Akt/mTOR/HIF1α pathway." (PMID 35281081, 2022). "Considering our results, we suggest to perform in situ mTOR activity profiling before administering mTOR inhibitor therapy for osteosarcoma patients." (PMID 35392503, 2022). "The IGF-1R/PI3K/mTOR cascade has been the subject of clinical trials in osteosarcoma with variable success." (PMID 35284040, 2022). "Calcium-binding protein A10 can accelerate glycolysis by mediating the AKT/mTOR signaling pathway in osteosarcoma, thereby enhancing malignancy of osteosarcoma cells." (PMID 36618348, 2022). "Activation of the mTOR pathway has been observed in osteosarcoma, however the inhibition of mammalian target of rapamycin (mTOR) complex 1 has had limited results in osteosarcoma treatment." (PMID 35392503, 2022). "Together, these results suggest that AOS-SO4 has a better antitumor effect in osteosarcoma by inhibiting MEK1/ERK/mTOR signaling, which is KSR1-dependent; thus, AOS-SO4 can be a new potential therapeutic candidate for the treatment of osteosarcoma." (PMID 35418575, 2022). "Drugs such as Duvelisib, Copanlisib, and Idelalisib showed potent inhibition of the PI3K/mTOR pathway and were approved clinically against many tumors, including osteosarcoma." (PMID 35656180, 2022). "Knockdown of Hsp90 was shown to inhibit autophagy by activation of the PI3K/Akt/mTOR pathway in osteosarcoma." (PMID 36012578, 2022). "Knock-down of mTOR in osteosarcoma cells, hepatocytes and adipocytes lengthens the cellular circadian period and reduces amplitude, while mTOR activation has the opposite effects." (PMID 35156088, 2021).